INS (insulin)
Diseases named in the same sentence as INS in open-access papers (continued):
Sharing a sentence is not in itself a finding about the gene and the disease.
diabetes (continued). "The influence of body fat on insulin action is important, and the association between obesity and insulin resistance plus type 2 diabetes mellitus (DM) has long been recognized." (PMID 26752053, 2016). "Overall, our data demonstrate that subordination stress is a potent stimulus for the downregulation of the insulin signaling pathway in liver and muscle and a major risk factor for the development of obesity, insulin resistance, and type 2 diabetes mellitus." (PMID 26946982, 2016). "Previous studies have demonstrated that shortage of protection induced by insulin was associated with weaken insulin sensitivity, and aerobic exercise partially improves insulin intolerance/sensitivity in diabetes and aging." (PMID 27019292, 2016). "Elevated levels of TNF-α in the liver are associated with the severity of diabetes, and IL-1β adversely affects the insulin signaling pathway and contributes to insulin resistance." (PMID 27929393, 2016). "According to the American Diabetes Association, DM can be defined as a group of metabolic diseases characterized by hyperglycaemia resulting from defects in insulin secretion, insulin action, or both." (PMID 28042834, 2016). "Diabetes mellitus is a chronic condition associated with the metabolic impairment of insulin actions, leading to the development of life-threatening complications." (PMID 27618891, 2016). "A position statement of the American Diabetes Association and the European Association for the Study of Diabetes recommends that metformin therapy be continued when insulin is initiated." (PMID 27152598, 2016). "Elevated serum EPA, DHA and DPA levels are associated with higher insulin sensitivity, providing a plausible explanation for the lower prevalence rates of diabetes." (PMID 27894336, 2016). "These and other clinical trials have also shown that the natural history of diabetes involves a progressive loss of beta cell function that consequently requires the use of multiple drugs to treat these patients, including insulin." (PMID 26909482, 2016). "Diabetes is a global health problem that is caused by impaired insulin production from pancreatic β-cells." (PMID 27672665, 2016). "Dietary restrictions, loss of independence and fingersticks/insulin were noted to be the most burdensome aspects of diabetes." (PMID 26813788, 2016). "Because of their family history, such people have an increased risk of developing diabetes and are likely to be insulin resistant." (PMID 27882410, 2016). "The effects of high glucose or insulin on the lungs have received interest in attempts trying to find an explanation to the association between diabetes and reduced lung function." (PMID 27212806, 2016). "Diabetes is caused by dysfunction to β-cells in the islets of Langerhans, disrupting insulin secretion and glucose homeostasis." (PMID 27681078, 2016). "Positive C‐peptide is used to assess ongoing endogenous insulin secretion, and is likely to be present in patients with diabetes caused by HNF1A and HNF4A mutations." (PMID 27330718, 2016). "Risk factors include age, male gender, duration of diabetes, uncontrolled glycaemia, height, overweight and obesity, and insulin treatment." (PMID 28058263, 2016). "Diabetes is insidious in onset and is chiefly due to beta-cell loss, with a blunted, delayed and prolonged insulin response to a carbohydrate load." (PMID 28702252, 2016). "Insulin use has previously been associated with a greater extent of coronary disease in diabetics, and duration of diabetes has also been associated with worse clinical outcomes." (PMID 26861208, 2016). "The most commonly used dosage of insulin in diabetes patients to cause antecedent and subsequent hypoglycaemia was 1-2 mU/kg/min." (PMID 27843452, 2016). "The effects of insulin-deficient Diabetes and/or oral treatment with alendronate, on the osteogenic, adipogenic, and chondrogenic commitment of BMPC were also studied." (PMID 27840829, 2016).
diabetes (continued). "Here the authors find blood-based biomarkers that reflect age-associated DNA methylation changes in human pancreatic islets associated with insulin secretion and diabetes." (PMID 27029739, 2016). "STZ, a highly cytotoxic agent of pancreatic β cells, induces diabetes by damaging the cells which causes reduction in insulin release." (PMID 26942038, 2016). "T2DM, on the other hand, is known as “non-insulin dependent” or “adult-onset” diabetes, caused by excessive elevated blood glucose levels that lead to insulin resistance." (PMID 28005998, 2016). "In other words, it does not seem that any relationship the UCSNP-43 polymorphism alone with diabetes involves impairment of insulin secretion in Iranian population." (PMID 27069562, 2016). "Diabetes mellitus includes a series of metabolic disorders due to the lack or diminished effectiveness of insulin secretion." (PMID 27547752, 2016). "Beside the well-known link between diabetes and cancer risk, the currently used therapeutic insulin analogues raised serious concerns due to their potential roles in cancer initiation and/or progression." (PMID 26983499, 2016). "T2DM is the most common form of diabetes, and is caused by a progressive insulin secretory defect against a background of insulin resistance." (PMID 27142520, 2016). "Recent studies show that JNK activation impairs insulin signaling transduction, resulting in diabetes-associated cognitive decline in the hippocampus of T2DM rats." (PMID 27793043, 2016). "Later, around 2000, several groups showed that alteration of the insulin signalling chain in the brain by knockdown of the insulin receptor or docking proteins causes brain insulin resistance, leading to a diabetes-like phenotype in mice." (PMID 27344314, 2016). "Alloxan treatment is known to induce diabetes by a massive destruction of the β-cells of the islets of langerhans which creates an insulin-deficient state leading to prolonged hyperglycaemia." (PMID 27003006, 2016). "Our aim was to identify factors associated with successful transfer from insulin to sulfonylureas in patients with permanent neonatal diabetes due to mutations in KCNJ11 (which encodes the inwardly rectifying potassium channel Kir6.2)." (PMID 27033559, 2016). "Lower NAART scores were also associated with higher fasting insulin (β=− 0.02 and P=0.02) and with diabetes ((β=− 3.81 and P<0.01)." (PMID 27642517, 2016). "The dysfunction or loss of the insulin-producing β cells causes diabetes mellitus, a disease that harms millions." (PMID 27399229, 2016). "Diabetes mellitus is a chronic metabolic disorder caused by either impaired insulin secretion or a reduction in its biological effectiveness." (PMID 27656241, 2016). "T1DM is known as “insulin dependent” or “juvenile-onset’ diabetes and caused due to the autoimmune destruction of the β-cells in the pancreas, accounting for about 5–10% of total DM cases worldwide." (PMID 28005998, 2016). "In general, levels of BMI, fasting C-peptide, HOMA2-%B, HOMA2-IR, and TG were found to be positively associated with AUC0–2 values, and HbA1c, HOMA2-%S, the duration of diabetes, the percentage of insulin usage, and HDL-C levels were inversely associated." (PMID 26649318, 2016). "The prevalence and high levels of anti-insulin antibodies (IA) have frequently been associated with brittle diabetes, lipodystrophy in the areas where the insulin is injected and/or poor metabolic control." (PMID 27617231, 2016). "Current research in diabetes reveals that a significant reduction in pancreatic β cell populations is the leading cause of the decrease in insulin production in T2D." (PMID 27092078, 2016). "Type 1 diabetes mellitus (T1DM) is due to deficient insulin secretion, inmost cases after autoimmune destruction of pancreatic beta cells." (PMID 26826879, 2016).
diabetes (continued). "In poorly regulated diabetes during pregnancy, fetal exposure to hyperglycemia causes early maturation of the insulin biosynthesis and release mechanisms with high insulin levels in the fetus." (PMID 27007259, 2016). "Experimental data in animal models of DR indicate that uncontrolled insulin-deficient diabetes markedly increases neuronal cell death in the retina." (PMID 27123463, 2016). "The role of serum calcium in diabetes development is unclear, but our data suggests that reduced Ca2+ levels in aged mice are associated with increased insulin secretion and glucose tolerance." (PMID 27441644, 2016). "Diabetes mellitus (DM) is a progressive and chronic metabolic disorder characterized by hyperglycemia caused by impaired insulin levels, insulin sensitivity, and/or insulin action." (PMID 27221050, 2016). "Type 2 diabetes (T2DM), a metabolic disease characterized by hyperglycemia caused by impaired insulin secretion (beta cell dysfunction) and insulin resistance of peripheral tissues, represents around 90% of diagnosed diabetes cases." (PMID 27328054, 2016). "When we manage patients with diabetes, it is clear that they represent a very diverse group of people, spanning all ethnicities, the young to the old, the slim to the morbidly obese, the insulin‐deficient to the markedly insulin‐resistant." (PMID 26802434, 2016). "It has been found that all-cause hospitalisation among adults with diabetes increased with insulin use, age, presence of chronic renal insufficiency, diagnosed hypoglycemia and a diabetes-related hospitalisation in the year prior." (PMID 27613597, 2016). "Among those with diabetes, metformin use was significantly associated with decreasing age, and decreased insulin use." (PMID 27513580, 2016). "Hypoglycemia is one of the biggest concerns for owners of cats with diabetes and is associated with larger doses of insulin." (PMID 27766967, 2016). "The data demonstrate that tiny changes in KATP channel activity can alter beta cell electrical activity and insulin secretion sufficiently to cause diabetes." (PMID 27118464, 2016). "Protein tyrosine phosphatase 1B (PTP1B) is known to promote the pathogenesis of diabetes and obesity by negatively regulating insulin and leptin pathways, but its role associated with colon carcinogenesis is still under debate." (PMID 27752061, 2016). "The finding that patients with diabetes due to potassium channel mutations can transfer from insulin to sulfonylureas has revolutionised the management of patients with permanent neonatal diabetes." (PMID 27033559, 2016). "In a study of Hispanics and African Americans, lower insulin clearance at baseline was associated with a higher risk of incident diabetes at five years of follow-up." (PMID 27846285, 2016). "Ageing can lead to reduced insulin sensitivity and loss of pancreatic beta cell function, predisposing individuals to the development of diabetes." (PMID 26474776, 2016). "In previous studies it has been reported that the decreased insulin action, insulin deficiency and/or insulin resistance in tissues is the primary cause of diabetes." (PMID 27625707, 2016). "SREBF1 (sterol regulatory element binding transcription factor 1), for which a significant association between methylation status and fasting glucose and 2-hour insulin was observed, has been linked to diabetes or related traits in human studies before." (PMID 27019061, 2016). "Lower verbal IQ, assessed by NAART, was associated with higher BMI (β=−0.28; P<0.01), elevated insulin (β= −0.02, P=0.02), and diabetes (β=− 3.18, P<0.01)." (PMID 27642517, 2016). "The ZDF rat is an ideal model to observe the natural progression of T2D from initial hyperinsulinemia to failure of β cells and loss of insulin production and then progressive diabetes in aging animals." (PMID 27153060, 2016).
diabetes (continued). "Bioluminescence has been utilized in the field of diabetes research by inserting the gene encoding luciferase under control by the mouse insulin promoter (MIP) enabling non-invasive longitudinal quantification of beta cell mass in the mouse." (PMID 27574523, 2016). "Autologoushuman iPS cells are not cleared by immune system post-transplantation; however,there are risks associated with the rejection of implanted insulin- producingcells by the same autoimmune mechanism that leads to the emergence of diabetes." (PMID 27795842, 2016). "It is worth to point out that insulin use was also associated with a higher risk of hypertension incidence in patients with diabetes." (PMID 27906989, 2016). "The dominant-negative effect of these mutants is caused by impairment of wild-type proinsulin intracellular transport and eventually, the insulin-deficient diabetes is compounded by apoptosis of beta cells that suffer from endoplasmic reticulum (ER) stress." (PMID 28702245, 2016). "The American Diabetes Association (ADA) and the European Association for the Study of Diabetes (EASD) published a consensus statement recommending insulin as a well-validated tier 1 option for the metabolic management of hyperglycaemia in T2D." (PMID 27391319, 2016). "Even after adjusting for several known risk factors of diabetes and insulin level, the association between the baseline TyG index and the risk of future diabetes remained statistically significant, indicating that the TyG index is an independent risk factor." (PMID 27682598, 2016). "Leptin can facilitate glucose utilization and improve insulin sensitivity, which has been implicated in the development of diabetes." (PMID 27195302, 2016). "With failing insulin secretion, glycemia increases until diagnostic thresholds for overt diabetes are exceeded." (PMID 27053136, 2016). "Since PCOS is a risk factor for diabetes, adding an agent that can potentially worsen insulin sensitivity and glucose levels is a concern that warrants further investigation." (PMID 28546815, 2016). "Diabetes mellitus is a chronic metabolic disease caused by a decrease in the production of insulin or sensitivity to insulin." (PMID 26810997, 2016). "The metabolic clearance rate of insulin (MCRI) has been shown to be a highly heritable trait that can influence the risk of developing diabetes." (PMID 27846285, 2016). "Most studies reported adjustment in their models for established diabetes risk factors including age, sex, triglyceride levels, BP or hypertension, measures of insulin or insulin resistance, and measures of overall or visceral adiposity." (PMID 26813008, 2016). "Diabetes is a metabolic disease caused by insufficient insulin secretion, insulin action or insulin resistance, which leads to a glucose metabolism disorder." (PMID 27585820, 2016). "Insulin secretion, insulin resistance, and homeostasis are important factors in the onset of diabetes, a disease that is associated with dysfunction of pancreatic β-cells." (PMID 27248987, 2016). "Attaining deficiency in insulin production in type 1 diabetes mellitus can occur by a variety of different mechanisms ranging from chemical ablation of the beta cells to breeding rodents that spontaneously develop autoimmune diabetes." (PMID 27595114, 2016). "Our results showed that resistant mutant mice suppressed diabetes in spite of the overexpression of Ghrl, a hormone whose antagonist had been shown to be able to normalize insulin secretion and hyperglycemia in Hnf1a deficiency." (PMID 27667715, 2016). "Among the non-hereditary mechanism are adipokines, mitogenic effect of insulin, the tumor-promoting effect of hyperglycemia and hyperinsulinemia in DM status, multiple usage of medication, diabetes-associated comorbidities, tissue-specific inflammation." (PMID 27105501, 2016).
diabetes (continued). "In general, failure to produce new adipocytes leads to an increase in large insulin-resistant adipocytes and a predisposition to developing diabetes and the metabolic syndrome." (PMID 27313625, 2016). "Insulin significantly contributes to the cost associated with diabetes, representing 24 to 36% of the treatment cost." (PMID 27907034, 2016). "This cytokine impairs insulin sensitivity and is linked to obesity and diabetes; moreover, it downregulates tyrosine kinase activity and interferes with signaling pathways." (PMID 26526677, 2016). "Diabetes mellitus is a group of multi-factorial metabolic diseases characterized by absolute or relative deficiencies in insulin production." (PMID 27542279, 2016). "Similar to the heart, insulin mediates a protective effect on cerebral blood vessels, and insulin resistance is implicated in increased stroke incidence in diabetes." (PMID 27514532, 2016). "Retinoic acid receptor-related orphan receptor alpha (RORA) plays a key role in the regulation of lipid and glucose metabolism and insulin expression that are implicated in the development of type 2 diabetes mellitus (T2DM)." (PMID 27556492, 2016). "The causes of diabetes development in GK rats are hyperglycaemia, impaired insulin secretion, overproduction of hepatic glucose, and peripheral insulin resistance." (PMID 27677945, 2016). "For instance, diabetes is a complex metabolic disease with hyperglycaemia resulting from either insulin deficiency (Type 1 diabetes) or impaired insulin action and insulin secretory function (Type 2 diabetes)." (PMID 27809830, 2016). "Another study has found a strong positive correlation between clusterin levels in HDL and insulin sensitivity which is important during pathology of diabetes-associated MCI." (PMID 27516739, 2016). "In our sample, Spoken Knowledge in Low Literacy Patients with Diabetes was independently associated with the following variables: schooling, use of insulin, duration of disease and functional health literacy." (PMID 28076599, 2016). "In most patients with heterozygous, dominant INS mutations, C-peptide is in the normal-low range at diabetes outset, but over time declines to undetectable levels as a consequence of ongoing apoptosis of the pancreatic beta cells." (PMID 26239141, 2016). "In a retrospective analysis of 756 patients who underwent bariatric surgery improvement in ALT was associated with an improvement in diabetes with ALT remaining elevated in those remaining on insulin therapy." (PMID 26856933, 2016). "In conclusion, although inhibition of glucagon action alone is insufficient to prevent diabetes in conditions of near-total insulin deficiency, it is beneficial when residual insulin action persists, as in STZ-treated Gcgr-/- animals." (PMID 27092792, 2016). "Several other risk factors were indicated in prolonged QT interval in diabetes, including systolic and diastolic blood pressure, hyperglycaemia, serum insulin level, microvascular diabetic complication and coronary heart disease." (PMID 27107571, 2016). "Though ineffective in alleviating preexisting diabetes, pretreatment of recombinant Reg3β was capable of minimizing the Stz-induced hyperglycemia and weight loss, by preserving serum and pancreatic insulin levels, and islet β-cell mass." (PMID 27767186, 2016). "Loss of insulin-mediated intra-islet suppression of glucagon production appears to be a contributor to the hyperglycemia of Akita mice, a model of insulin-deficient diabetes." (PMID 28702245, 2016). "The underlying mechanisms behind why statins cause diabetes are unclear but adverse effects on both insulin secretion and insulin resistance have been suggested." (PMID 26986474, 2016). "In this study, we aimed to determine the association of diabetes and preadmission insulin and metformin use with sepsis outcome and host response." (PMID 27495247, 2016).